CCNY (cyclin Y)
Diseases named in the same sentence as CCNY in open-access papers (continued):
Sharing a sentence is not in itself a finding about the gene and the disease.
cancer (9 papers, 2014 to 2025). A tumor composed of atypical neoplastic, often pleomorphic cells that invade other tissues. "Whereas both CDK16 and CCNY have been implicated in cell proliferation and cancer, the physiological substrates of the CDK16/CCNY complex have yet to be identified." (PMID 30992425, 2019). "Furthermore, CDK14, CDK16, CDK18 and cyclin Y have all been linked to cancer cell proliferation, migration or cancer drug resistance." (PMID 28057719, 2017). "Cyclin Y expression was upregulated in three cancer cell lines (H1299, A549, and PC9) compared with that in human bronchial epithelial Beas-2B cells." (PMID 40083692, 2025). "CCNY is reported to regulate the proliferation, migration, and invasion of cancer cells through the Wnt/β-catenin signaling pathway." (PMID 35449080, 2022). "Different functions have been attributed to CCNY including the regulation of cancer cell proliferation, Wnt signalling as well as the control of adipogenesis." (PMID 33153214, 2020). "Although both proteins have been recently implicated in cancer pathogenesis, it is still unclear how the CDK16/CCNY complex exerts its biological activity." (PMID 30992425, 2019). "Based on that study, we assessed the effects of siRNA-mediated cyclin Y knockdown on cell proliferation and cell death in cancer cell lines." (PMID 25593992, 2014). "Cyclin Y, a member of the cyclin family, is involved in various biological processes, such as memory flexibility, spine plasticity, autophagy, adipogenesis, and cancer progression 9-12." (PMID 40083692, 2025). "A notable study showed that inhibition of the 5hmC epigenetic modification in CCNY/CDK16 promoters impaired the activity of renal cancer stem cells, suggesting the potential effects of CDK16 on cancer stem cells (CSCs)." (PMID 35449080, 2022). "As shown by GSCA, except CCNY, CCNT2, and CCNC, all cyclin genes were differentially expressed in different cancers, among which the number of genes in COAD was the highest, with 16 genes differentially expressed in total." (PMID 33996604, 2021). "Despite the targeting effect of cyclin Y on PCTAIRE1, cell proliferation was not suppressed by cyclin Y knockdown (data not shown), suggesting that other mechanisms that do not involve cyclin Y likely participate in PCTAIRE1 activation in cancer cells." (PMID 25593992, 2014).
tumor (9 papers, 2017 to 2026). "Cyclin Y has been implicated in various cellular processes such as cell growth, proliferation, autophagy, and tumor progression." (PMID 40083692, 2025). "To further validate these effects in vivo, we established Cyclin Y stable knockdown cells and found a reduction in both tumor size and weight in nude mice injected with Cyclin Y knockdown cells compared with those injected with control cells." (PMID 40083692, 2025). "Previous studies from our and other laboratory indicate that CCNY play a crucial role in tumor progression." (PMID 34222253, 2021). "The levels of EMT markers were also detected to determine the function of CCNY making during tumor metastasis." (PMID 34222253, 2021). "Down‐regulation of CCNY expression will significantly decrease the growth and division speed of tumour cells." (PMID 30411496, 2019). "The expression levels of CCNO were higher in tumour cell lines than in the normal one, while CCNY and CCNG1 exhibited higher expression in HT-29 cells." (PMID 30087414, 2018). "Furthermore, after the irradiation of both cohorts of mice, the sg-Cyclin Y groups exhibited a reduction in tumor size and weight in comparison to the sg-control groups." (PMID 40083692, 2025). "A weak signal of CCNY was detected in both tumor and normal tissues." (PMID 28860486, 2017). "The results suggest that CCNY might be a new tumor biomarker for diagnosis and therapy." (PMID 34222253, 2021). "Additional clinical validation using TMAs revealed that CCNY, TET2, and phosphorylated PRC1were significantly upregulated in tumor tissues." (PMID 40665337, 2025). "First, significantly higher staining intensities of phosphorylated PRC1, CCNY, and TET2 were detected in tumor tissues compared to normal tissues." (PMID 40665337, 2025). "CCNY, the key cyclin binding partner responsible for activating CDK16, has been shown to influence cell proliferation and tumor progression in NSCLC." (PMID 40665337, 2025). "The canonical Wnt signaling pathway is activated by the mitotic CDK14/cyclin Y complex via phosphorylation of the LRP6 coreceptor, which leads to anti-inflammatory signaling that inhibits tumor growth." (PMID 37258567, 2023). "The TMA analysis revealed increased levels of CCNY, TET2, and phosphorylated PRC1 in tumor tissues." (PMID 40665337, 2025). "As anticipated, the in vivo experiments validated that knockdown of CCNY in H1299 and H1975 cells reduced their tumorigenic activity in the nude mice, accompanied by decreased expression of KI67 while increased expression of C-Cas3 in tumor tissues." (PMID 40665337, 2025). "In the present study, we found no statistical difference regarding the expression of CCNY in healthy and tumor tissues." (PMID 28860486, 2017).
infection (1 paper, 2018). The state of being infected such as from the introduction of a foreign agent such as serum, vaccine, antigenic substance or organism. "Individuals with at least one copy of the CA insertion at rs58000832, an intergenic insertion between CREM and CCNY, had 2.42 times increased odds of diarrhea-associated infection within the first year of life compared to individuals with no copies of this insertion." (PMID 30228239, 2018).
CCNY also shares sentences with these, for which no sentence is quoted: lung adenocarcinoma (2 papers); Obesity (2); Alzheimer disease (1); autoimmune thyroid disease (1); melanoma (1); prostate carcinoma (1); systemic lupus erythematosus (1).